CXCR2 (C-X-C motif chemokine receptor 2)
Diseases named in the same sentence as CXCR2 in open-access papers (continued):
Sharing a sentence is not in itself a finding about the gene and the disease.
tumor (continued). "Treatment with CXCR1/2 inhibitor SX-682 dramatically depleted the population of intratumoral CXCR2+ MDSCs and increased the infiltration of CD8+ and CD4+ T cells to suppress pancreatic cancer growth in a mouse iKRAS PDAC model, enhancing the survival time of tumor-bearing mice." (PMID 38672552, 2024). "Given the elevated expression of ELR+CXCL/CXCR2 proteins in human primary macrophages, we set out to investigate RCT001's capacity to effectively modulate the polarization of macrophages-like towards both the anti-tumor M1 phenotype or the pro-tumor M2 phenotype." (PMID 38504270, 2024). "Moreover, IHC staining of the tumor tissues derived from shNKX2‐1/LL2 cells orthotopically implanted into mouse lungs also showed elevated expression of ITGAM, CEACAM8, ELANE, and CXCR2 as compared to the control." (PMID 39113226, 2024). "Increased CXCR2 expression in tumor cells supports cell survival, epithelial-mesenchymal transition, and recruitment of myeloid-derived suppressor cells (MDSC) to the tumor microenvironment, which promote tumor progression and protect tumors from the body’s natural antitumor immune response." (PMID 38324085, 2024). "CXCR2 is not exclusively expressed by neutrophils, and may also be expressed by endothelial cells and tumor cells, meaning that CXCR2 could mediate migration of those non-neutrophil cells." (PMID 38786066, 2024). "To test whether inhibiting PMN tumor infiltration or TAN proangiogenic activity can be used as therapy to curb tumor growth, we utilized commercially available small molecule inhibitors Reparixin (a CXCR2 inhibitor) and NSC405020 (allosteric MMP14 inhibitor)." (PMID 38329810, 2024). "Therefore, to help improve tumor trafficking to tumor tissues, in the studies reported here we also evaluated the impact of addition of a chemokine receptor (CXCR2) to the CAR construct, to enhance trafficking to a CXCL8 gradient, which is present in many tumor types." (PMID 38554158, 2024). "In the same study, CXCR2+ MPO+ (Myeloperoxidase) cells infiltrated spontaneous intestinal tumors in Apcmin/+ and AhCreER; Apcfl/+; Ptenfl/fl mice and CXCR1/2 blocking pepducin treatment suppressed tumor infiltration of MPO+ cells and adenoma formation concurrently." (PMID 38786066, 2024). "Moreover, targeting CXCR2+ immunosuppressive neutrophils, either independently or in combination with additional treatments, enhances antitumor immune activity; specifically, that of CD8+ T cells, and reduces tumor burden across different cancer types." (PMID 38358352, 2024). "Contrastingly, CXCR2 blockade did not affect other tumor-infiltrating myeloid populations." (PMID 38067390, 2023). "The CXCR2 and ADRA1A closely interacted, and the signaling network of related genes indicated that the function module might involve in the immune response regulation in the tumor microenvironment." (PMID 36611170, 2023). "The present study also brought evidence of NLRP7 involvement in the differentiation of tumor cells through the induction of embryonic markers such as NANOG, NOTCH1 and OCT3/4, and the activation of their survival through the induction of genes, such as CD74 and its co-receptor CXCR2." (PMID 36980199, 2023). "Chemokines secreted by TAMs, including CCL3, CCL5, CCL15, CCL18, CXCL8 and CXCL12, promote tumor metastasis, angiogenesis, cancer cell survival, immunosuppression and resistance of cancer cells after chemotherapy via CCR1/5, CCR5, CCR1, CCR8, CXCR1/CXCR2, CXCR4, respectively." (PMID 36173487, 2023). "To further understand the molecular mechanism by which the FGL2-blocking scFv induces CD69+CD8+ TM cell generation, we analyzed CyTOF data for chemokine receptors (i.e., CCR2, CXCR3, CXCR2, and CX3CR1) that may affect T cell infiltration and recruitment to tumor sites." (PMID 36759517, 2023). "Furthermore, they observed strong spatial contiguity between CXCL1-expressing tumor islands and CXCR2+ PMN-MDSCs, with CD8+ T cells being conspicuously absent from these areas." (PMID 37455286, 2023).
tumor (continued). "In addition to VEGF, MDSCs have also been discovered to secrete various bioactive factors, including CXC chemokine receptor 2 (CXCR2), CXCR4, IL-6, TGF-β, and metalloproteinases, that could facilitate tumor migration and metastasis and promote angiogenesis." (PMID 36817414, 2023). "The expression of CXCL7 and CXCR2 was found to be negatively correlated with disease-free survival (DFS) and OS in patients with liver metastatic CRC, suggesting that the CXCL7/CXCR2 signaling pathway may be involved in tumor recurrence and progression." (PMID 35837284, 2022). "CXCR1 and CXCR2 are expressed in a variety of immune and non-immune cells, including tumor cells." (PMID 35837284, 2022). "Moreover, both CXCR2+ neutrophils and intratumoral GZMKhigh CD8+ TEM positively correlated with tumor size, supporting the existence of a GZMKhigh CD8+ TEM -neutrophils crosstalk that might favor tumor progression." (PMID 36347862, 2022). "Chemokine analysis highlighted CCR2, CXCR2, CXCR4 and C5aR ligands/chemoattractants as possible targets to decrease the immune myeloid suppressive cells in NMIBC, but also revealed a complex chemokine crosstalk, which deserve particular attention to design novel anti-tumor-treatments." (PMID 36613562, 2022). "transduced human T cells with a GPC3-CAR together with CXCR2; compared with CAR-T cells without CXCR2, these cells exhibited identical cytotoxicity but significantly increased migration in vitro, as well as accelerated in vivo trafficking and tumor-specific accumulation in a xenograft tumor model." (PMID 35432319, 2022). "As a matter of fact, blocking CXCR1 or CXCR2 in neutrophils upon coincubation with supernatant from various chemokine-producing carcinoma cell lines abrogated NET formation, which argues for the involvement of CXCR1 and CXCR2 ligands in tumor-mediated NET formation." (PMID 35979369, 2022). "Awaji found that KRAS mutation could promote the secretion of paracrine factors such as IL4, IL10, and IL13 in tumor cells and simultaneously activate CXCR2 signaling in CAFs, resulting in the formation of a secreted CAF phenotype by activating NF-κB signaling and promoting tumor progression." (PMID 36076911, 2022). "Furthermore, the intracellular CXCR2 has been shown to activate the NFKB pathway in solid tumors, an action that releases different tumor-promoting cytokines to support the surviving blasts through bypassing the targeted therapy (indicated by a red dash arrow in schematic diagram of last figure)." (PMID 35625776, 2022). "Furthermore, MIF promotes tumor proliferation, migration, invasion, angiogenesis and chemotherapy resistance via binding to different receptors, including CD74, C-X-C motif chemokine receptor 2 (CXCR2), CXCR4, and CXCR7." (PMID 35842634, 2022). "These contrasting results could be explained by at least two mechanisms: first, inhibitors target both CXCR1 and CXCR2, and the differential role of these receptors in tumor biology has not yet been demonstrated." (PMID 35158948, 2022). "Two small molecule CXCR2 antagonists, SCH-527123 and SCH-479833, were reported to be robust antimetastatic therapeutics in human CRC liver metastasis, which acts at the metastatic site by declining the tumor vascularization and enhancing the malignant cell apoptosis." (PMID 35954156, 2022). "In vivo, lipopolysaccharide (LPS) induces CXCR2+ and polymorphonuclear myeloid-derived suppressor cells (PMN-MDSC) accumulation through the production of TLR4-dependent CXCL1, controls CCA tumor cells to form an immunosuppressive microenvironment, and facilitates CCA tumor growth." (PMID 36147461, 2022). "SB265610, a CXCR2 antagonist, may reverse immunosuppression by inhibiting the chemotaxis of MDSC to the tumor, thereby promoting the anti-tumor immunity of CD8+ T cells and inhibiting tumor immune escape." (PMID 36457492, 2022). "CXCR2/4 activity may be one major mediator in MDSC recruitment and MDSC related tumor metastasis." (PMID 34689842, 2021).
tumor (continued). "In parallel, we showed that this antagonist led to a lower vessel density and decreased infiltration of microglia/macrophages with a consecutive tumor volume reduction using an immunocompetent GBM rodent model focusing on the CXCL2/CXCR2 signaling pathway due to lacking the IL8 expression in mice." (PMID 33807899, 2021). "In addition, among the surface MIF receptors, surface expression of CXCR2 and CXCR4 in M-MDSC, and CXCR4 and CXCR7 in G-MDSC were decreased in response to rSmeg-hMIF-hIL-7, indicating that rSmeg-hMIF-hIL-7 suppressed the infiltration of MDSC into tumor." (PMID 34389619, 2021). "There, an upregulation of IL8 and CXCR2 was demonstrated within the tumor after anti-angiogenic treatment with VEGF-pathway inhibitors and a decrease of tumor-derived endothelial-like cells as well as tumor stem cells after application of the CXCR2-antagoist SB225002." (PMID 33807899, 2021). "The recruitment of neutrophils in TME is mainly regulated by chemokine receptor CXCR2 and it has been reported that TNFa-activated mesenchymal stem cells (MSCs) releasing CXCL1, CXCL2 and CXCL5 efficiently recruited CXCR2 positive neutrophils into the tumor, promoting BC metastasis." (PMID 34885027, 2021). "There was a strong increase in CD11b+ CD11c− Ly6Ghi Ly6Clo cells in in the spleen of PyMT−Cxcr2−/− animals compared to PyMT animals, which was similar to Cxcr2−/− animals suggesting that this increase was related to Cxcr2 inactivation and not to the presence of a tumor." (PMID 34070438, 2021). "Due to this dramatic down-regulation in chemokine receptors’ expression on TANs, we hypothesized that the chemokines binding CXCR2 and CXCR4 (i.e., CXCL1/CXCL2 and CXCL12, respectively) could be responsible for the differential infiltration of NDN and LDN into the tumor." (PMID 34680231, 2021). "Importantly, direct exposure of NLRP3 activating alum crystals or of the NLRP3 inhibitor as well as of blocking antibodies directed against CXCR2 or of the CXCR4 inhibitor did not significantly change the proliferation of SCC VII or 4T1 tumor cells in vitro." (PMID 34876407, 2021). "However, the role of CXCR2 and neutrophils in cancer is not fully elucidated yet and most likely not congruent in all tumor types." (PMID 34503058, 2021). "In summary, our data reveal that a lack of Cxcr2 provides TANs with pro-tumor effects." (PMID 34070438, 2021). "Altogether, our results suggest the occurrence of an intricate CXCL2/CXCL8-CXCR2 axis in the modulation of cisplatin sensitivity by OC cells, thus corroborating with an important role of TME and a potential autocrine effect of CXCL2/CXCL8 on CXCR2 expressed by tumor cells." (PMID 34038868, 2021). "All the results collectively indicated that antagonism of CXCR2 could impacted functional CD8+ T cell and DC infiltration into tumor sites in the CRC mouse model, which indicated that these treatments could change the TME in the CRC mouse model into a worse situation." (PMID 34025668, 2021). "Thus, CXCR2 signaling represents a promising additional therapeutical target in GBM treatment to overcome TMZ-induced resistance, as single therapies often fail to target all tumor cells due to GBM heterogeneity." (PMID 34681839, 2021). "In the KPC model, CXCR2 blockade by genetic or pharmacologic means reduces recruitment of myeloid cells into the PDAC microenvironment (especially neutrophils), permitting T-cell dependent suppression of tumor growth, an effect which can be augmented by PD-1 inhibition to improve survival." (PMID 33304355, 2020). "Similarly, CAR T cells overexpressing CXCR1 or CXCR2 can significantly reduce tumor burden, without obvious toxicity, in various solid tumor xenografts." (PMID 32423475, 2020). "However, treatment with IR induced the expression of chemokine receptors CXCR1 and CXCR2 in tumour cells independent of PTEN status." (PMID 32743555, 2020).
tumor (continued). "Leukocyte recruitment to the tumor site is mediated by inflammatory chemokines from the CXC subfamily (CXCL1, -2, -5, -6, and -8) as well as from the CC group (CCL2, -3, and -5), which attract leukocytes: neutrophils bearing receptors CXCR2 and CCR2-positive monocytes." (PMID 32456359, 2020). "In addition, suppressing the action of proangiogenic cytokines induced by HEYL using a small molecule inhibitor of the CXCl1/2/3 receptor, CXCR2, in combination with the anti-VEGF monoclonal antibody, bevacizumab, significantly reduced tumor growth of MDA-MB-231 xenografts." (PMID 33520697, 2020). "Indeed, we showed that treatment with a CXCR2 inhibitor dramatically reduced lymph node metastasis, while primary tumor growth was not affected." (PMID 31390756, 2019). "Using these models, we found that co-expression of CXCR1 and CXCR2 with an αvβ6-specific CAR resulted in a significant increase in T-cell migration towards recombinant or tumor-derived IL-8, without alteration of CAR-mediated cytolytic activity or cytokine release." (PMID 31091832, 2019). "Although some evidence indicates that CXCR2 inhibition could prevent recruitment of CD11b+ Gr1+ myeloid cells in PTEN−/− prostate tumors, it remains unclear whether Ly6G+ neutrophil infiltration at the tumor site is impaired." (PMID 31616408, 2019). "Although further investigations are necessary to elucidate the detailed mechanisms of the CXCLs–CXCR2 axis dependency of PDAC progression, blocking CXCLs–CXCR2 axis in the crosstalk between tumor and stromal cells could be a promising therapeutic strategy for PDAC." (PMID 30659170, 2019). "Furthermore, tumor exoRNAs can activate lung epithelial cell TLR3 to recruit neutrophils due to the expression of chemokine receptors (CXCR1, CXCR2, CXCR4, andCCR2) being higher in tumor-bearing Tlr3−/− mice, consequently inducing lung premetastatic niche formation." (PMID 30849983, 2019). "As already mentioned, the binding of IL-8 to CXCR2 in non-muscle cells is known to activate STAT and ERK signaling, but also to activate NF-κB and p38 MAPK signaling, and each of these signaling pathways is implicated in tumor-induced skeletal muscle atrophy." (PMID 31769424, 2019). "Moreover, in vivo treatment using a CXCR2 antagonist (SB265610) inhibited tumor growth in HM-1 tumor-bearing mice, but not in HM-1-shSnail tumor-bearing mice." (PMID 29703902, 2018). "Interestingly, Cxcr2 does not appear to be required for neutrophil recruitment to the tumor-initiating microenvironment, suggesting that neutrophil response to the early TME is more like their response to wounds than infected tissue." (PMID 30185911, 2018). "Treatment of mice engrafted with wild-type EO771 cells with a Cxcr2 antagonist impaired tumor growth, reduced myeloid-derived suppressor cells and regulatory T cells, while increasing macrophages, dendritic cells, NK cells and the penetration of CD8+ T cells into the tumor bed." (PMID 29632317, 2018). "Therefore, antagonism of CXCR2 has been demonstrated to work in combination with traditional chemotherapeutic agents in decreasing cellular senescence and malignancy, primarily through a decrease in MDSC tumor infiltration." (PMID 30081463, 2018). "Intriguingly, in mutants for the related receptor Cxcr2, we did not observe any decrease in neutrophil recruitment to transformed astrocytes, further suggesting the tumor-initiating microenvironment is similar to the wound neutrophil chemotactic microenvironment." (PMID 30185911, 2018). "CXCR2 was not present on the surface of Ly6Ghi myeloid cells within the tumor microenvironment." (PMID 28915554, 2017). "Furthermore, the expression of CXCR2 by innate myeloid cells in the primary tumor microenvironment is fundamental for PDAC metastasis, as supported by two observations: either CXCR2 inhibition or depletion of neutrophils/myeloid-derived suppressor cells reduces metastases." (PMID 29156578, 2017).
tumor (continued). "However, the role of its receptor CXCR2, which expresses in tumor cells and neutrophils membrane was not clarified in our previous study." (PMID 28415702, 2017). "Upon blockage of CAF-secreted CXCL1 signaling by 500 ng/ml CXCL1 antibody or by 400 nM CXCR2 inhibitor SB225002, CAF-enhanced ROS increase following radiation was attenuated in KYSE-30 and in KYSE-150, suggesting CAF-secreted CXCL1 enhanced ROS increase following radiation in tumor cells." (PMID 28518141, 2017). "Furthermore, we also revealed that CXCL5 secreted by tumor cells was able to promote CRC migration through ERK/Elk-1/Snail-mediated EMT (Epithelial mesenchymal transition) and invasion via the AKT/GSK3β/β-catenin/MMP7 pathway in a CXCR2-dependent manner." (PMID 28356111, 2017). "Unexpected results enhancing mRNA levels of CCL20 rather than CXCL1/2 in CXCR2-driven ovarian progression indicate the diversity and complex of chemokine network between cell culture system with homogenous interaction and tumor progression via heterogeneous interaction with other cell types." (PMID 27723802, 2016). "Furthermore, while identifying the presence of CXCR2 macromolecular signaling complex in PDAC cells, a recent study provided additional functional evidence for the role of CXCR2 signaling in mediating in vitro and in vivo tumor cell growth." (PMID 26771140, 2016). "More effective tumor suppression may be achieved with dual CXCL1 and CXCR2 blockage." (PMID 26104296, 2015). "Our data showed a consistent result with previous studies that CXCR2 expression positively correlated with tumor depth, lymph node metastasis and TNM stage, which implied that CXCR2 expression might synergize gastric cancer proliferation, invasion and metastasis." (PMID 26497045, 2015). "Interestingly, 83.3% of CXCR2 positive/IL-8 negative cases exhibited IL-6 immunoreactivity, implying a redundancy of the angiogenic mechanisms in this tumor." (PMID 24593195, 2014). "However, the results do not imply CXCR2 is a tumor suppressor, and further studies on the role of CXCR2 per se will be summarized in our next study." (PMID 25011526, 2014). "The absence of CXCR2 in the tumor microenvironment also prevented colon cancer cell growth." (PMID 24376747, 2013). "Treatment with this selective CXCR2 antagonist reduced the tumor number on the lung surface of CC-LR mice not exposed to NTHi lysate by ~67% (3-fold, 54 ± 5 without SBZ versus 18 ± 2 with SBZ) and after NTHi exposure by ~23% (1.3-fold, 108 ± 11 without SBZ versus 83 ± 21 with SBZ)." (PMID 24321240, 2013). "Moreover, RETAAD tumor cells attracted PMN-MDSC in vitro and this attraction was significantly reduced when PMN-MDSC were treated with either SB265610 or SB225002, two specific inhibitors of CXCR2." (PMID 21980263, 2011). "Notably, CXCR2 serves as a key receptor for multiple chemokines (e.g., CXCL1, CXCL2, CXCL8) and is critically involved in the recruitment of myeloid-derived suppressor cells (MDSCs), a potent population of immunosuppressive cells, into the tumor microenvironment." (PMID 41347146, 2025). "Additionally, preclinical studies demonstrate the accumulation of CXCR2+ PMN-MDSCs in the RMS microenvironment and metastatic niches, indicating that these cells are recruited to the TME via chemokines such as CCL2 and CXCL12, where they interact with tumor cells to maintain immunosuppression." (PMID 41007114, 2025). "Additionally, the use of SB225002 (a CXCR2 inhibitor) in conjunction with Withaferin A (a natural anticancer agent that induces ferroptosis through lipid peroxidation in vivo) and α‐PD‐1 (an anti‐PD‐1 antibody) to block MDSC infiltration in tumor‐bearing mice led to increased survival rates." (PMID 40452814, 2025). "Furthermore, IL‐17 A may induce chemokine‐induced angiogenesis (CXCL8/CXCR2 axis) and promote tumor progression independent of the VEGF pathway." (PMID 38515019, 2024).